CYLD (CYLD lysine 63 deubiquitinase)
Diseases named in the same sentence as CYLD in open-access papers (continued):
Sharing a sentence is not in itself a finding about the gene and the disease.
melanoma (continued). "In addition, the expression of CYLD, which is a deubiquitinating enzyme that is a key mediator in the necroptotic pathway, was found to be decreased in chronic lymphocytic leukemia (CLL) and malignant melanoma." (PMID 31122251, 2019). "Together, this report emphasizes that MEG3 acts as an antitumor lncRNA for malignant melanoma by regulating miR-499-5p/CYLD axis; MEG3 may be a novel and crucial biomarker in patients with melanoma and can be used as a promising molecular target in the treatment of malignant melanoma." (PMID 29808164, 2018).
cylindroma (24 papers, 2009 to 2025). "We present a rare case of multiple cylindromas of the scalp associated with a novel CYLD pathogenic variant." (PMID 39355720, 2024). "We report a 61‐year‐old male with multiple scalp cylindromas, leading to genetic testing that identified a novel pathogenic variant in the CYLD gene, highlighting the importance of genetic testing in these cases." (PMID 39355720, 2024). "The identification of this novel CYLD pathogenic variant expands the spectrum of genetic alterations associated with cylindromas and highlights the importance of genetic testing in patients with multiple adnexal tumours." (PMID 39355720, 2024). "Here, we report a case of a 61‐year‐old male presenting with multiple cylindromas of the scalp, prompting genetic testing that revealed a novel pathogenic variant in the CYLD gene." (PMID 39355720, 2024). "The Cylindromatosis (CYLD) gene is located on 16q12-13 and loss of CYLD alleles has been reported to be one of the causes of cylindroma." (PMID 37393410, 2023). "Our impression, especially in light of CYLD mutation, the fundamental alteration in familial and sporadic cylindromas, is that the deposition of this hyalinized basement membrane material most resembles that seen in cylindroma." (PMID 32892208, 2021). "CYLD mutation has been most extensively studied in the context of cutaneous cylindromas in both syndromic manifestations, such as Brooke–Spiegler syndrome, and sporadic tumors." (PMID 32892208, 2021). "Here, we report that the presence of CYLD mutation defines a relatively frequent subset of HPV-related HNSCC that exhibits histopathologic features reminiscent of cylindroma and distinctive genomics." (PMID 32892208, 2021). "Mutations of CYLD, which encodes an enzyme regulator of NF-κB, have been previously characterized as causative of syndromic and sporadic cylindroma and were recently described in HNSCC." (PMID 32892208, 2021). "While both are carcinomas related to CYLD alterations, cylindrocarcinoma consists of a malignant proliferation associated with a precursor cylindroma." (PMID 32892208, 2021). "In this study, the presence of cylindroma-like histologic appearance, as principally defined by the presence of basement membrane inclusions, was significantly correlated with CYLD mutation in the context of AC." (PMID 32461623, 2020). "While CYLD-mutated ACs share some histologic features with cutaneous cylindroma, multiple histologic differences are readily apparent." (PMID 32461623, 2020). "One case with a single CYLD mutation (P42L; allele frequency = 60%) was predicted germline; the case showed cylindroma-like histology." (PMID 32461623, 2020). "Rare reports of anal carcinoma (AC) describe histologic resemblance to cutaneous cylindroma, but mutations in the tumor suppressor CYLD, the gene responsible for familial and sporadic cylindromas, have not been systematically investigated in AC." (PMID 32461623, 2020). "A recent molecular genetic study of cutaneous cylindromas, spiradenomas, and spiradenocarcinomas found CYLD mutations in nearly all cylindromas and some spiradenomas." (PMID 32461623, 2020). "Cylindroma-like histology had a sensitivity and specificity of 73% and 92%, respectively, for the presence of CYLD mutation." (PMID 32461623, 2020). "Cylindromas are characterized by mutations in CYLD and approximately two- thirds of sporadic cylindromas have also been reported to carry the MYB-NFIB fusion gene, which leads to overexpression of MYB, analogous to adenoid cystic carcinoma." (PMID 31101826, 2019). "Somatic or germline CYLD mutations were found in 12/12 cylindroma patients (matched tumor-germline cases) with mutations also being observed in spiradenoma and high-grade spiradenocarcinoma cases." (PMID 31101826, 2019). "Loss-of-function mutations were also detected in CYLD in several cylindroma cases (PD29695a, PD29696a, and PD29700a) and in one low-grade spiradenocarcinoma (PD29676a)." (PMID 31101826, 2019).
cylindroma (continued). "Germline mutations in the tumour suppressor gene CYLD are recognized to be associated with the development of multiple cutaneous cylindromas." (PMID 29569226, 2018). "We encountered a patient in our cohort of well‐characterized CYLD mutation carriers who presented with breathlessness and were surprised to discover multiple pulmonary cylindromas." (PMID 29569226, 2018). "Here we present data that extends the phenotype seen in CYLD mutation carriers to include multiple pulmonary cylindromas." (PMID 29569226, 2018). "Previous studies of inherited cylindromas have highlighted the frequent presence of bi‐allelic truncating CYLD mutations as a recurrent driver mutation." (PMID 26969893, 2016). "Here, we investigated inherited cylindromas from several families with germline CYLD mutations for the presence of MYB activation." (PMID 26969893, 2016). "The finding of MYB activation in these inherited tumours is intriguing, since the underlying mechanism behind formation of inherited cylindromas has been shown to be largely limited to a germline mutation of CYLD and loss of heterozygosity at the CYLD locus." (PMID 26969893, 2016). "The clinical presentation of multiple, rare, skin appendage tumours called cylindromas has been attributed to germline mutations in the tumour suppressor gene CYLD (OMIM 605018)." (PMID 25737804, 2015). "CYLD is a gene whose loss or mutations predispose to the development of human cylindroma, a particular type of hair follicle benign tumor." (PMID 26652480, 2015). "The finding that hyperactive Wnt signaling in human cylindroma skin tumors arises from mutations in CYLD validates the clinical significance of CYLD-mediated deubiquitination of Dvl." (PMID 24594309, 2014). "Our series connects a distinctive histopathology of cylindroma-like basaloid carcinoma of the anus with mutations in CYLD, a gene responsible for both syndromic and sporadic cylindromas, confirming both a morphologic and genetic relationship with cutaneous cylindroma." (PMID 32461623, 2020). "CYLD mutations are also present in sporadic cylindromas and some spiradenomas." (PMID 32461623, 2020). "For instance, Brooke–Spiegler syndrome, caused by mutations within CYLD—a tumor-suppressor gene regulating NF-κB activation—is an autosomal-dominant disorder characterized by multiple benign cutaneous adnexal tumors (most commonly spiradenomas, cylindromas, and trichoepitheliomas." (PMID 35205753, 2022). "Morphologically similar lesions, such as adenoid cystic carcinoma or salivary basal cell adenocarcinoma, may arise in the oral cavity and oropharynx, necessitating awareness of oropharyngeal SCC variants, including those with cylindroma-like features and CYLD mutation." (PMID 32892208, 2021). "Within our cohort of ACs, CYLD mutations characterize a surprisingly large subset (13%), with distinct clinical and genomic features and, predominantly, a striking cylindroma-like histopathology, representing a genotype-phenotype correlation which may assist in classification of AC." (PMID 32461623, 2020). "We chose to explore the presence of MYB–NFIB fusion transcripts in tumours from patients with germline CYLD mutations, to determine whether such fusions were present at a similar frequency to that seen in sporadic cylindroma and ACC, which share histological similarities." (PMID 26969893, 2016). "However, it remains to be determined whether MYB–NFIB fusion‐positive sporadic dermal cylindromas also carry bi‐allelic CYLD mutations, as these two changes could potentially act synergistically in promoting cylindroma development." (PMID 26969893, 2016).
cylindroma (continued). "In Brooke-Spiegler syndrome (BSS), which is characterized by multiple adnexal tumors, including cylindromas, spiradenomas, and trichoepitheliomas, a defect in the CYLD gene located on chromosome 16 at position 12.1 is typically observed." (PMID 40666062, 2025). "In head and neck, as well as in anal carcinoma, CYLD mutations were associated with high-risk HPV status and frequent cylindroma-like histopathology." (PMID 37387450, 2023). "In these parameters, CYLD-wildtype HNSCC with cylindroma-like histologic features resembled CYLD-mutant HNSCC, which often showed cylindroma-like features." (PMID 32892208, 2021). "Our group recently demonstrated an analogous subset of HPV-positive, CYLD-mutant basaloid anal carcinomas with cylindroma-like histologic features." (PMID 32892208, 2021). "CYLD-mutant cylindroma-like basaloid carcinomas of the anus represent a significant subgroup of ACs with distinctive genetic and histologic features and near-universal detection of HPV-positivity." (PMID 32461623, 2020). "We reveal somatic or germline alterations of the CYLD gene in 15/15 cylindromas and 5/17 spiradenomas, yet only 2/24 spiradenocarcinomas." (PMID 31101826, 2019). "To investigate the biological significance of MYB overexpression in cylindroma, given the lack of MYB–NFIB fusion transcripts, we used siRNAs to knock down MYB mRNA expression in cultured primary CYLD‐defective cylindroma cells." (PMID 26969893, 2016). "To further examine the role of MYB overexpression in the molecular pathogenesis of inherited cylindromas, we silenced the expression of MYB in CYLD‐defective cylindroma cells, using RNA interference." (PMID 26969893, 2016). "For example, loss of CYLD, a key de-ubiquitinating enzyme that controls NEMO function, has been linked to a predisposition to cylindroma." (PMID 19826422, 2009). "In addition, CYLD-wildtype HNSCC with cylindroma-like histology showed a higher frequency of NFKBIA truncating alterations (12% [4/34] vs. 1% [4/425], p = 0.0014)." (PMID 32892208, 2021). "Although several investigators have noted the histologic resemblance of reportedly rare ACs to cylindroma, to our knowledge, CYLD mutation has not been described in detail for AC." (PMID 32461623, 2020). "CYLD-mutant basaloid carcinomas, however, show permeative growth and frequently display necrosis, often in a comedo pattern, features unusual for cutaneous cylindroma." (PMID 32461623, 2020). "Importantly, compared with CYLD-wildtype AC, CYLD-mutant AC showed over ninefold higher frequency of cylindroma-like histology, as principally designated by the presence of basement membrane inclusions within tumor cell aggregates (73% vs. 8%, p < 0.0001)." (PMID 32461623, 2020). "Notably, among cylindroma-like cases, hyaline globule inclusions tended to be abundant in the CYLD-mutant group and focal in the CYLD-wild type group." (PMID 32461623, 2020). "In line with this reasoning, it will be interesting to study whether NF‐κB inhibitors can down‐regulate MYB and inhibit the proliferation of CYLD‐defective cylindroma cells." (PMID 26969893, 2016). "In addition, TRK inhibitors could also represent a treatment option for tumors that lack functional CYLD, such as cylindroma." (PMID 41168867, 2025). "While these studies lacked histomorphologic data which would enable closer correlation with the cases in our cohort, the demonstrated relationship between CYLD mutation and HPV-driven carcinogenesis may be analogous to our series of CYLD-mutant cylindroma-like ACs." (PMID 32461623, 2020). "With respect to the CYLD-wildtype cases with cylindroma-like hyaline globule inclusions, we have considered that these cases may contain non-CYLD, as-yet uncharacterized mutations activating related pathways to promote a similar histogenesis, although this requires additional study." (PMID 32461623, 2020). "Notably, we also show that MYB drives the proliferation of CYLD‐defective cylindroma cells." (PMID 26969893, 2016).
cylindroma (continued). "CYLD and DNMT3A were identified as statistically significant driver genes in cylindroma." (PMID 31101826, 2019). "This resulted in a significant inhibition of MYB target genes and proliferation of cylindroma cells from three independent tumours, suggesting that MYB activation drives the growth of CYLD‐defective cylindromas and potentially also the growth of MYB–NFIB‐positive sporadic cylindromas." (PMID 26969893, 2016). "The CYLD-mutant cases without accompanying cylindroma-like features may be partly attributable to sampling error; most biopsies were partial and may have missed cylindroma-like foci." (PMID 32461623, 2020).
hepatocellular carcinoma (23 papers, 2010 to 2025). A malignant tumor that arises from hepatocytes. "MicroRNA-362-5p promotes tumor growth and metastasis by targeting a cytoskeleton-associated protein, Cylindromatosis (CYLD), in hepatocellular carcinoma." (PMID 33379338, 2020). "Hellerbrand and Massoumi have found that mutation or disruption of the activity of CYLD in animals aggravated acute as well as chronic liver injury and promoted development and progression of hepatocellular cancer." (PMID 27738385, 2016). "CYLD induces the death of hepatocellular carcinoma (HCC) cell lines when treated with doxorubicin through NF-κB activation." (PMID 40896706, 2025). "The attenuated expression of A20 and CYLD is shown in patients with leukemia/lymphoma and Cezanne is down-regulated in hepatocellular carcinoma." (PMID 37893484, 2023). "Previous studies have proved that the expression level of CYLD in the nucleus was related to the prognosis of hepatocellular carcinoma, but the mechanism was unclear." (PMID 35579924, 2022). "Several studies show that miR-454 functions as an oncogene in colorectal cancer, hepatocellular carcinoma, non-small cell lung cancer and induce the oxaliplatin resistance in gastric carcinoma cells by targeting CYLD." (PMID 33892654, 2021). "Experimental models have shown that CYLD loss promotes aggressive behavior in various malignancies, including cutaneous SCC, pancreatic carcinoma, and hepatocellular carcinoma." (PMID 32892208, 2021). "The tumor-suppressing function of CYLD has been detected in many cancers, including breast, oropharynx, colon, and hepatocellular carcinomas." (PMID 32708712, 2020). "In recent years, reduction of CYLD expression has been detected in various cancers such as breast cancer, glioblastoma, and hepatocellular carcinoma." (PMID 31635163, 2019). "Five genes with de novo damaging alleles PIK3CA, TLN1 CYLD, and MAP2K1, are linked with cholangio- and hepatocellular carcinomas in addition to congenital syndromes and conditions related to tissue overgrowth." (PMID 27955658, 2016). "Downregulation of CYLD induced tumor cell proliferation and consequently contributed to the aggressive growth of hepatocellular carcinoma." (PMID 27738385, 2016). "Increased CYLD suppressed the development of hepatocellular carcinoma and gastric cancer." (PMID 29808164, 2018). "Six genes carrying DNVs were associated with human developmental disorders involving epithelial, connective or bone morphologies (PXDN, RTEL1, ANKRD11, MAP2K1, CYLD, ACAN) and four linked with cholangio- and hepatocellular carcinomas (PIK3CA, TLN1 CYLD, MAP2K1)." (PMID 27955658, 2016). "In hepatocellular carcinoma cells, CYLD downregulation leads to apoptosis resistance." (PMID 24495516, 2014). "In addition, expression of CYLD is down-regulated in several other types of human tumors including hepatocellular carcinoma, melanoma, colon cancer, and multiple myeloma." (PMID 23825949, 2013). "Down-regulation of CYLD expression enhances the resistance to chemotherapy in breast cancer and hepatocellular carcinoma (HCC)." (PMID 38287022, 2024). "miR-362-5p was significantly upregulated in hepatocellular carcinoma (HCC) and involved in HCC progression through CYLD to activate the NF-κB signaling pathway." (PMID 31929841, 2019). "Reduced CYLD expression has been reported in different tumor entities, including hepatocellular carcinoma (HCC)." (PMID 25329885, 2014). "For instance, in hepatocellular carcinoma (HCC), CYLD expression was down-regulated and involved in the resistance towards treatment with doxorubicin, 5-FU, and cisplatin." (PMID 36376983, 2022). "In addition, hepatocellular carcinoma tissues and cell lines have also been found to have up-regulated miR-501-5p, and overexpression of miR-501-5p could enhance tumor cell proliferation by targeting CYLD." (PMID 31307515, 2019).
hepatocellular carcinoma (continued). "Unlike A20, the inactivation of CYLD is found in blood cancers, including leukemia, and a downregulated expression of Cezanne is reported in solid cancers, such as hepatocellular carcinoma." (PMID 37893484, 2023). "In the present study, the clinicopathological relevance of the deubiquitinase CYLD was assessed in a series of 95 human hepatocellular carcinoma (HCC) samples, obtained from patients undergoing resection or liver transplantation as treatment of early stage HCC." (PMID 25329885, 2014). "Recently, reduced CYLD was also found in human carcinomas, such as hepatocellular carcinoma and colon cancer, as compared with nonneoplastic tissue." (PMID 20414373, 2010).